APP (amyloid beta precursor protein)
Diseases named in the same sentence as APP in open-access papers (continued):
Sharing a sentence is not in itself a finding about the gene and the disease.
cognitive decline (continued). "In the amyloid precursor protein/presenilin 1 (APP/PS1) transgenic mice, puerarin increased NrF‐2 and its downstream antioxidant molecule heme oxygenase 1 (HO‐1) and alleviated oxidative stress damage, blocked amyloid beta (aβ) deposition, and rescued cognitive decline." (PMID 34964013, 2021). "So far, all clinical trials involving β-secretase inhibitors have been terminated due to side effects and/or lack of positive effects, and some studies even report cognitive decline possibly due to negative effects on putative physiological functions of APP and/or Aβ." (PMID 32456694, 2020). "Because several clinical trials targeting Aβ have failed to ameliorate cognitive decline, further studies may shift to the role of the APP intracellular domain (AICD)." (PMID 32580938, 2020). "Moreover, a developing of an astrocyte conditional STAT3 knockout in APP/PS1 transgenic mice leads to an anti-inflammatory profile, which could mediate Aβ clearance by microglial cells and reduce cognitive decline." (PMID 33050466, 2020). "The very encouraging results included increased proteasome-mediated turnover of amyloid precursor protein (APP) and β-secretase (which cleaves APP to generate β-amyloid peptide), concomitant with lowered levels of β-amyloid, lowered mortality and protection against cognitive decline." (PMID 32235805, 2020). "Moreover, genetic ablation of p66Shc in an AD mouse model (APP/PS1) leads to a reversal of age-dependent cognitive decline, independent of Aβ levels and plaque formation." (PMID 30459314, 2018). "Despite examining results from two different cognitive tests (MWM and NOR), five different mouse models (Tg2576, APP, PS1, 3xTg, and APP(OSK)-Tg) and considering potential gender and age differences, no statistical relationship could be identified linking Aβ to mouse cognitive decline in AD." (PMID 25362040, 2015). "An alternative mechanism was that CMV infection might directly affect AD pathogenesis by increasing local inflammatory response to various antigens, possibly including Aβ, increasing amyloid precursor protein (APP) production and formation of toxic amyloid protofibrils, leading to cognitive decline." (PMID 25157230, 2014). "Moreover, in a recent study conducted on APP/PS1 mice model it has been demonstrated the Hepc overexpression in astrocytes provokes a reduction in iron levels in cortical and hippocampal neurons with a significant improvement in terms of cognitive decline and Aβ plaques aggregation." (PMID 38913042, 2024). "Interestingly, APP cKO mice did not have the same cognitive decline at 6 or 8 months old." (PMID 33402196, 2021). "Importantly, hippocampal cyclic adenosine monophosphate (cAMP), p-PKA, p-CREB and BDNF levels were significantly increased in the APP/PS1 mice after RJ treatment, indicating that the cAMP/PKA/CREB/BDNF pathway might be related to the ameliorative effect of RJ on cognitive decline." (PMID 30687079, 2018). "Additionally, increased expression of amyloid precursor protein (APP) and Aβ oligomers in hippocampal neurons, as well as reduced antioxidant activity (SOD and GSH levels), were observed, suggesting that EMP exposure could contribute to cognitive decline and neurodegenerative changes." (PMID 40076887, 2025). "The two-month-old 5xFAD mice showed an increase in p-APP in cortex total homogenates without JNK activation and cognitive decline." (PMID 36980245, 2023). "In the APP/PSI AD mouse model, BCG immunization reversed their cognitive decline but did not reduce the burden of Aβ in the brain." (PMID 35208878, 2022). "They found a significant up-regulation of APP TOT and APP KPI in both AD and FTLD patients compared to the controls, although the severity of cognitive decline did not correlate with the expression of up-regulation in FTLD patients." (PMID 34440494, 2021).
neuroblastoma (378 papers, 2005 to 2026). Neuroblastoma (NB) is the most common solid, extracranial childhood tumor. "Alterations of AD-related miRNA levels are observed in EVs extracted from SH-SY5Y cells expressing the Swedish mutation of APP695 (SHSwe) and mouse neuroblastoma N2a cells expressing human amyloid precursor protein (APP)." (PMID 39643909, 2024). "In a recent study, we reported that APP-CTFs accumulate in the mitochondria-enriched fraction of human neuroblastoma cells expressing human APP harboring the Swedish familial mutation (SH-SY5Y-APPswe) that promotes Aβ and APP-CTFs production." (PMID 35665766, 2023). "In a modern study, the authors described that APP-CTFs gather in the mitochondria-supported segment of neuroblastoma cells in human-articulating APP sheltering the Swedish familial mutation that encourages APP-CTFs and Aβ construction." (PMID 37109499, 2023). "For instance, the overexpression of NUCB1 in neuroblastoma N2a cells is associated with reduced levels of mRNA of the amyloid precursor protein (APP)." (PMID 37047165, 2023). "Similar results were observed in Aβ-treated N2a neuroblastoma cells and APP/PS1 transgenic cell lines associated with elevated Aβ levels, leading to cell death." (PMID 37760073, 2023). "SK-N-SH neuroblastoma cells were transduced with vectors expressing mutations in genes that are found in FAD: human APP with both K670N/M671L (Swedish) and V717I (London) mutations (APPSL) as well as presenilin 1 with the ΔE9 mutation (PSEN1ΔE9)." (PMID 37739965, 2023). "A human neural cell culture model consisting of a human neuroblastoma cell line overexpressing human APP with double FAD mutations was established in vitro." (PMID 34073900, 2021). "In this study, we characterized the structural and functional alterations at MAM, mitochondria, and ER/microsomes in a mouse neuroblastoma cell line (N2A) overexpressing the human amyloid precursor protein (APP) with the familial Swedish mutation (APPswe)." (PMID 34440085, 2021). "The main goal of our study was to investigate the structural alterations at MAM using an in vitro model of AD, namely the mouse neuroblastoma cell line (N2A) overexpressing the APP familial Swedish mutation (APPswe)." (PMID 34440085, 2021). "In N2a neuroblastoma cells expressing the APP Swedish mutation, C-terminal fragments of APP resulting from cleavage by β- and gamma-secretases were enriched within secreted exosomes and selectively internalized by recipient neurons." (PMID 34987360, 2021). "To study AD protein aggregation, we used a mouse neuroblastoma (N2a) cell line that was stably transfected with human APP harboring the Swedish mutation (N2a-APPSWE)." (PMID 33810433, 2021). "In this study, the mouse neuroblastoma cell line N2a which harbors stable overexpression of APP with wild-type (WT) was used, and Swedish mutations were designed as N2a/APP and N2a/APPswe stable cell lines, respectively." (PMID 32751716, 2020). "Overexpression of wild type or mutant APP caused mitochondrial fragmentation in M17 neuroblastoma cells and primary neurons, which was blocked by beta-APP cleaving enzyme (BACE1) inhibitor, suggesting that Aβ induced this effect." (PMID 32471464, 2020). "Overexpression of ABCA2 in vitro in human embryonic kidney cells and N2a neuroblastoma cells was associated with increased expression of the APP gene through increased transcription and promotes cleavage of APP by BACE1." (PMID 32098382, 2020). "We then investigated expressions of S1T and ER stress markers in the neuroblastoma SH-SY5Y cell line stably expressing the Swedish mutated APP (APPswe: SH-SY5Y APPswe)." (PMID 31795302, 2019). "In another cell system, that is, mouse neuroblastoma Nm2a cells with overexpression of human mutated amyloid precursor protein (APP) cells, CSZ was shown to increase CREB phosphorylation." (PMID 31191308, 2019).
neuroblastoma (continued). "We next examined the consequence of inhibiting Drp1/Fis1 interaction in another model of AD disease, neuroblastoma cells expressing a mutant form of APP, a mutation that is associated with FAS, found in a Swedish family (KM670/671NL)." (PMID 29464060, 2018). "Consistently, the CHME3 microglial cells displayed a pro-inflammatory phenotype when co-cultured with human neuroblastoma cells SH-SY5Y stably expressing the amyloid beta precursor protein (APP) harboring the APP695 Swedish mutation (SHswe)." (PMID 30200996, 2018). "For these studies, we used the Neuro 2A (N2A) cells, a mouse neuroblastoma cell line stably expressing human APP carrying the K670 N, M671L Swedish mutation (N2A‐APPswe)." (PMID 27896923, 2017). "In the present study the ferrireductase enzyme Steap3, and putative ferrireductase α-synuclein, were both associated with high APP amyloidogenic processing and β-amyloid production in neuroblastoma cells." (PMID 28187176, 2017). "Considering that previous research has shown that fibroblasts from patients carrying the APPsw mutation and human neuroblastoma cells overexpressing the mutation secrete higher levels of Aβ, we investigated APP cleavage in the astrocyte populations." (PMID 26398935, 2015). "To investigate endogenous accumulations of full-length APP and Aβ under pathological situations simulating those in the AD brain, we used mouse neuroblastoma cells stably expressing human APP Swedish mutation (N2aSwe cells)." (PMID 26244661, 2015). "Several reports in neuroblastoma cells or dissociated neurons have previously linked APP expression to neurite outgrowth." (PMID 24684730, 2014). "We demonstrated that Sw-APP transfected human neuroblastoma cells over-producing Aβ had increased susceptibility to cytotoxicity under oxidative stress." (PMID 23300647, 2012). "In neuroblastoma cells, hnRNP C was shown to enhance the translation of mRNA that encode amyloid precursor protein (APP), a protein that, when aberrantly processed, is the major constituent of cerebral amyloid plaques found in patients with AD." (PMID 23060744, 2012). "Transfection of APP-deficient neuroblastoma cells with APP resulted in increased surface localization of the ATP synthase a-subunit and in extracellular APP and amyloid-beta inhibiting the extracellular generation of ATP." (PMID 22523685, 2012). "Constructs encoding the C-terminal part of APP (C99) were used to transfect human neuroblastoma cells in order to overexpress C99." (PMID 19707560, 2009). "We increased cellular NAD+ levels by incubating the Aβ (N2s: N2a mouse neuroblastoma cells expressing the Swedish K595N and M596L mutations in Amyloid-beta precursor protein) and tau cells (HEK293 cells Tau P301L) with NAD+ precursor nicotinamide mononucleotide (NMN, 0.5 mM) for 24 h." (PMID 39394148, 2024). "To explore the effects of liensinine and neferine on intracellular Aβ toxicity, we used Aβ-induced neurotoxicity in APP695swe SH-SY5Y cells, which constructed by stably transfecting with the human Swedish APP mutation APP695 in SH-SY5Y human neuroblastoma cells, as in vitro Aβ cell model." (PMID 37891552, 2023). "As an in vitro model of familial AD, mouse neuroblastoma cells expressing either wild-type APP, APP with the Swedish mutation or the double-mutated human APP and PS1, showed that familial AD mutations are associated with the activation of classical apoptotic pathways." (PMID 35659112, 2022). "We further asked whether Kaem and Rhap could reduce hAβ1–42 production by using N2a mouse neuroblastoma cells expressing the Swedish K595N and M596L mutations in Amyloid-beta precursor protein/APP (APPSwe)." (PMID 34992270, 2022).
neuroblastoma (continued). "In the present study, vitamin B12 treatment of SH-SY5Y cells led to a significant increase in both phosphatidylcholine plasmalogens and phosphatidylethanolamine plasmalogens in wild-type neuroblastoma cells and in a cellular AD-model expressing the Swedish mutation of APP." (PMID 36010649, 2022). "In this regard, the brain-derived EVs from 3xTgAD mouse (APP Swedish mutation, Tau P301L, and Presenilin 1 M146V) or from neuroblastoma cells show an accumulation of APP-CTFs induced by the inhibition of the γ-secretase, a molecular complex involved in Aβ peptide generation." (PMID 33362690, 2020). "Similarly, an increase in the fission protein Fis1 is associated with a high rate of mitochondrial fragmentation in neuroblastoma cells that overexpress the mutated human amyloid precursor protein (APP)." (PMID 33227902, 2020). "In addition, MGO is associated with enhanced aggregation of Aβ in MC65 human neuroblastoma cells and AGEs regulate amyloid precursor protein (APP) processing and Aβ accumulation." (PMID 31331077, 2019). "Regarding in vitro studies, the exposure of human (SK-N-SH) and mouse (Neuro-2a) neuroblastoma cells to silica NPs (SiNPs) (10 μg/mL/24 h) raised the intracellular content of Aβ in both cell lines, which was associated with increased APP and reduced NEP protein levels." (PMID 25914621, 2015). "Similarly, a decrease in TGF-β signaling in cultured neuroblastoma cells was found to cause neuronal degeneration and to increase levels of secreted Aβ and β-secretase-cleaved soluble APP." (PMID 22470449, 2012). "Thus, GBE significantly attenuated mitochondria-initiated apoptosis and decreased the activity of caspase 3, a key enzyme in the apoptosis cell signalling cascade, in neuroblastoma cells stably expressing an AD-associated double mutation in APP." (PMID 20808761, 2010). "The oxidase-deficient cells were unable to kill the APP-expressing neuroblastoma cells." (PMID 17094809, 2006). "Furthermore, using a neuroblastoma cell line stably expressing APP, it was found that mutations in the phosphorylation and N-glycosylation sites not only reduced the presence of APP and FPN on the cell surface but also caused intracellular iron retention." (PMID 40071123, 2025). "To elucidate the mechanism by which Pon1 depletion impacts Phf8 and its downstream effects on mTOR, autophagy, and APP, we first examined whether the findings in Pon1−/− mice can be recapitulated in cultured mouse neuroblastoma N2a-APPswe cells that overproduce Aβ from a mutated human APP transgene." (PMID 36899882, 2023). "In addition, altered levels of AD-related miRNAs have been found in EVs derived from human neuroblastoma SH-SY5Y cells stably expressing APP695 Swedish mutation (SHSwe) and mouse neuroblastoma N2a cells expressing human APP, compared to the responding controls." (PMID 36510311, 2022). "In an in vitro model of AD-associated neuroinflammation, viral mimetic poly(I:C) challenge of amyloid precursor protein (APP)-overexpressing neuroblastoma cells elicited coordinated induction of LIMASI and key inflammatory mediators." (PMID 41827846, 2026). "It inhibits tau hyperphosphorylation and reduces APP expression in APP-transfected human neuroblastoma cells." (PMID 41601969, 2026). "In vitro studies demonstrated enhanced cellular uptake of Tf-Ost-Lip in human brain endothelial cells (hCMEC/D3) and amyloid precursor protein-transfected neuroblastoma cells (APP-SH-SY5Y), with improved BBB penetration and cytoprotective effects." (PMID 40869046, 2025). "Both IPA and melatonin were demonstrated to improve mitochondrial respiratory rate in APP-expressing neuroblastoma cells." (PMID 40942152, 2025). "Previously, we demonstrated that ouabain binding to Na,K-ATPase prevents Aβ42-induced activation of Src kinase and the subsequent change in the level of the amyloid precursor protein (APP) in human neuroblastoma SH-SY5Y cells." (PMID 41458975, 2025).
neuroblastoma (continued). "Iron levels have been demonstrated to influence the translation of APP protein mRNA in astrocytes and neuroblastoma cells by a mechanism like iron control of ferritin L and ferritin H mRNA translation through IREs in their 5’-UTRs." (PMID 40438504, 2025). "To evaluate the effect of marinobufagenin, bufalin, and digoxin on APP level in human neuroblastoma cells we used the 100 nM concentration, which was previously used for ouabain." (PMID 41458975, 2025). "In neuroblastoma cells expressing the human APP gene, IPA increased mitochondrial membrane potential and respiration rate, and reduced free radical production." (PMID 40942152, 2025). "The expression of APP mRNA in astrocytes and neuroblastoma cells is influenced by iron levels in the brain." (PMID 40438504, 2025). "Rong and associates (2017) discovered that using the human neuroblastoma cell line, SK-N-SH, NDRG2 modulates amyloid precursor protein (APP) processing, leading to an increase of amyloid β (Aβ) peptides via the BACE1 and GGA3 pathways." (PMID 40378957, 2025). "In this study, the effects of marinobufagenin, bufalin, and digoxin on APP production and Src kinase activation were evaluated in neuroblastoma cells, both in the absence and presence of Aβ." (PMID 41458975, 2025). "In the present study, we investigated the effects of Hup A on amyloid precursor protein (APP) proteolysis in SH-SY5Y neuroblastoma cells." (PMID 39056711, 2024). "Posiphen and phenserine are a new class of small compounds that reduce the development of Aβ in the brain while blocking the APP 5′-UTR IRE RNA-directed translation of APP in astrocytoma and neuroblastoma cell lines and in rats." (PMID 39770511, 2024). "In the present study, RNA interference was employed to investigate the impact of ACOT7 knockdown on APP metabolism in neuroblastoma SK-N-SH APPwt cells." (PMID 39026992, 2024). "We also revealed that Miro1 localization to mitochondria is impacted by APP-CTFs accumulation and Aβo treatment in differentiated neuroblastoma cells." (PMID 38806484, 2024). "A previous study using human and mouse neuroblastoma cell culture suggests that inhibition of GSK-3β by AR-A014418 decreases APP cleavage by BACE1, reducing the production of Aβ peptides." (PMID 38574297, 2024). "Human neuroblastoma SH-SY5Y cells have been widely used as experimental model for assessing APP proteolysis under physiological condition as well as studying tau physiology." (PMID 39056711, 2024). "Activation of CRHR1 by CRH has been shown to increase the release of APP in rat cerebellar neurons, in human neuroblastoma IMR32 cell line, and in mouse hippocampal HT22 cells." (PMID 38706793, 2024). "As in differentiated neuroblastoma cells, the colocalization of APP-CTFs with mitochondria was observed in both the soma and dendrites." (PMID 38806484, 2024). "When iron is chelated in a neuroblastoma cell line, APP protein synthesis is drastically decreased, demonstrating the involvement of iron in the regulation of APP translation." (PMID 37834241, 2023). "In a study, the effect of ebselen on amyloid precursor protein (APP) processing in human neuroblastoma SH-SY5Y cells was also evaluated." (PMID 37465348, 2023). "T3 had been shown to alter the splicing of APP genes and the secretion of this molecule in neuroblastoma cells, and to regulate the cellular and extracellular content of APP." (PMID 36897166, 2023). "Over-expression of LRP10 in human neuroblastoma SH-Sy5y cells led to an accelerated APP transport from TGN to the plasma membrane with increased APP maturation and reduced Aβ production." (PMID 37340466, 2023). "In neuroblastoma cells, overexpression of APP leads to elevated levels of Aβ1-40 with reductions in cellular respiration, ATP levels, and COX activity; the activity of complex III was also high." (PMID 37958934, 2023). "MiR-200b and miR-429 downregulate APP mRNA and protein expression in primary mouse hippocampal neurons and human neuroblastoma cells." (PMID 38003448, 2023).